MYC (MYC proto-oncogene, bHLH transcription factor)
Diseases named in the same sentence as MYC in open-access papers (continued):
Sharing a sentence is not in itself a finding about the gene and the disease.
tumor (continued). "This dual contribution makes the interplay between MYC and RTKs not only essential for tumor maintenance but also a significant obstacle to effective treatment." (PMID 40076599, 2025). "Consistently, in MYC-overexpressing tumor cells, LAT1/LAT3 inhibition compromises metabolic reprogramming and, in particular, the depletion of LAT1 significantly inhibits glucose and Gln uptake." (PMID 41008653, 2025). "When the tumor is located near the ventricles, there is a risk of choroid plexus invasion, and if molecular testing indicates MYC gene amplification, we must be highly vigilant for the occurrence of tumor ECM and take early preventive and therapeutic measures." (PMID 41239669, 2025). "Tumor-suppressor miRNAs like the let-7 family repress oncogenes such as RAS and MYC, and their loss contributes to unchecked cell proliferation." (PMID 41154621, 2025). "In cancer cells, MYC gene dysregulation is achieved due to the activation of tumor-specific super-enhancers." (PMID 40216980, 2025). "The role of glycolysis in tumor resistance and the central role of MYC in glycolysis and cancer have drawn attention to targeting MYC and tumor metabolism 58-60." (PMID 39990228, 2025). "SIRT6 is a tumor suppressor that inhibits cell proliferation and tumorigenesis by partially repressing c-MYC-dependent genes involved in ribosome biogenesis." (PMID 38954215, 2025). "For example, in neuroblastoma models, combining MDM2 inhibitors with MYC inhibitors delayed tumor growth and prolonged survival, compared to MDM2 inhibitor monotherapy." (PMID 40002221, 2025). "This signature, tightly regulated by MYC, enables tumor cells to adapt to proteotoxic stress and supports their proliferation and survival." (PMID 40718795, 2025). "While the PVT1 locus contains oncogenic MYC enhancers, PVT1 transcription was shown to serve a tumor suppressive role by curbing MYC transcription." (PMID 40743223, 2025). "To investigate mechanisms of MB tumor development, we queried MYC genomic localization along with gene expression profiling and observed that MYC is targeted to active chromatin as well as transcriptionally repressed regions regulated by JARID1B." (PMID 41415380, 2025). "Preclinical studies have shown that MYC inhibition significantly enhances tumor immunogenicity, increases T-cell infiltration, and potentiates immune checkpoint blockade efficacy." (PMID 40365020, 2025). "Of those studied here, STAT3 and MYC are important in both type I and type III latency, and depletion or inhibition of these proteins causes EBV to reactivate and/or the tumor cells to die." (PMID 40354417, 2025). "SRSF1 depletion suppresses glycolytic genes in tumor cells by limiting bZIP and MYC transcription factors, thereby eliminating the metabolic barrier to T cell activation." (PMID 39837814, 2025). "The results showed that similar as the MYC siRNA, delivery of miR-218 also suppresses MYC expression in TECs and normalizes tumor vessels." (PMID 40303332, 2025). "Analysis of TCGA-LUAD data revealed that elevated IGF2BP3 expression correlates with advanced tumor stages and poor patient survival, consistent with its established role in stabilizing pro-survival transcripts such as c-MYC and CD44." (PMID 40313617, 2025). "This is due to an overlapping metabolic rewiring in activated T-cells and MYC-transformed lymphocytes, similar to that which occurs in tumor cells (with the activation of proto-oncogenes such as c-Myc)." (PMID 39940843, 2025). "Our study confirms that LIN28B facilitates EC progression through the upregulation of MYC and mediates immunosuppressive tumor microenvironment reprogramming." (PMID 40740861, 2025). "By dynamically altering cell states, inducing treatment escape‐associated TFs (such as SOX2, ASCL1), and activating pathways like PI3K/AKT and MYC, the tumour further enhances its ability to adapt to immune attack and metabolic stress." (PMID 40847555, 2025).
tumor (continued). "MYC is a transcription factor known to be involved in tumor development and modulation of the tumor microenvironment." (PMID 41153362, 2025). "The KRASG12V/MYC tumor cells also displayed the “Warburg effect”, as revealed by a higher rate of glycolysis quantified by Seahorse metabolic flux experiments." (PMID 40550880, 2025). "Mechanistically, scRNA‐seq analysis revealed upregulation of the chemo‐resistance‐related MYC‐Notch‐non‐NE axis and a more immune‐responsive tumor microenvironment in peripheral ES‐SCLC." (PMID 39974662, 2025). "These intrinsic events within tumor cells enhance ER stress‐associated ubiquitylation and degradation of the EZH2/MYC axis by triggering the UBA6‐UBE2Z‐FBXW7 ubiquitin cascade." (PMID 39823459, 2025). "In ARMS, MYC is frequently upregulated and contributes to the tumor’s aggressive behavior by promoting cellular proliferation, inhibiting apoptosis, and enhancing metastatic potential." (PMID 40076599, 2025). "DNA methylation result of this patient indicated G3 MB with MYC amplification, and MRI of whole brain and spinal cord showed tumor dissemination and metastasis." (PMID 40229260, 2025). "In contrast, downregulation of hallmark E2F targets and MYC targets V1 with RETA hints at impaired cancer cell proliferation and tumor suppression." (PMID 40094000, 2025). "The miR-34a is a key regulator of tumor suppression controlling the expression of several targets involved in the cell cycle (c-MYC, E2F, CDK4 and CDK6), apoptosis (BCL2 and SIRT1) and tumor-associated invasion (c-MET)." (PMID 40755967, 2025). "In tumours, the overexpression of MYC activates RNA polymerase I (Pol I) and III (Pol III) and translation initiation factors such as eIF4E, enhancing protein synthesis and promoting metabolic reprogramming." (PMID 40525649, 2025). "Bioinformatics and molecular docking suggested that MYC-related signaling contributes to the anti-tumor activity of CMSP in OSCC." (PMID 41347093, 2025). "Performing single-cell CNV analyses on MYC-amplified tumour samples (subgroups II/V), we identified a subclonal MYC amplification in six of seven samples." (PMID 40335697, 2025). "Although low levels of MYC are able to drive the proliferation of non‐transformed cells and oncogenesis, high levels of deregulated MYC activate apoptosis and tumor surveillance pathways." (PMID 40488968, 2025). "Once stabilized and highly expressed, MYC acts as a “master regulator” of transcription, activating genes involved in proliferation, aerobic metabolism, angiogenesis, and tumor invasiveness." (PMID 40076599, 2025). "Methylation of CpG sites belonging to the MYC gene appears to be higher in DNA from normal tissues than from tumor tissues." (PMID 39858030, 2025). "MYC interacts with critical pathways such as cell cycle regulation, apoptosis, and angiogenesis, amplifying tumor aggressiveness and resistance to standard therapies." (PMID 40076599, 2025). "Previous in vitro cell experiments have demonstrated that NCL regulates the anti-tumor immune function of CD8 + T cells via targeting the MYC/TXNIP axis." (PMID 40346484, 2025). "Module 2 featured correlations among CD8 FTL+ Tex cells, CD4 Treg cells, plasma B cells, and two tumor meta-programs (MYC and unfolded protein response)." (PMID 40890106, 2025). "Consistent with the DEN-CCl4 model, hepatic Npc1 knockout inhibited TGF-β signaling and tumor progression in the MYC-driven HCC model." (PMID 39762312, 2025). "In neuroendocrine cells, MYC activates Notch to dedifferentiate tumor cells, promoting a temporal shift in SCLC from ASCL1+ to NEUROD1+ to YAP1+ states." (PMID 40433367, 2025). "NEUROD1-driven SCLC (SCLC-N) accounts for ~15% of SCLC cases and is characterized by high NEUROD1 expression, often co-expressed with MYC, which drives rapid tumor proliferation." (PMID 40333678, 2025).
tumor (continued). "Cells in both tumor models retained proliferative and immature characteristics, as evidenced by c-MYC overexpression and increased MKI67 expression, and decreased expression of MAP2 and GFAP compared to their respective controls." (PMID 40917877, 2025). "Generalizing these results to other tumor types requires validation in additional MYC‐dependent models." (PMID 41025936, 2025). "Given MYC’s involvement in tumor growth and metastasis, it stands out as a promising target for the development of targeted therapeutic strategies." (PMID 40076599, 2025). "By reprogramming both the transcriptome and the metabolome, the EWS-FLI-1/MYC axis creates a phenotype optimized for tumor survival, growth, and invasion." (PMID 40076599, 2025). "c-MYC is a well-established oncogene transcription factor that governs tumor cell proliferation, apoptosis, and metabolic reprogramming." (PMID 40710353, 2025). "These convergent pathways reinforce the rationale for trials that combine WNT/MYC inhibitors with immunotherapy in CMS2/3 tumours." (PMID 40594059, 2025). "E2F1 expression was significantly increased by the greatest multiple in the high stemness score group compared to SOX2 and MYC, as well as in the tumor and adjacent normal tissues group, early(I + II) and advanced stage (III + IV) group." (PMID 40886002, 2025). "Next, we performed pharmacokinetics analysis of the MYC-mRNA drug in the serum of the tumor-bearing mice treated with the drug." (PMID 40949131, 2025). "From the substrate standpoint, either MYC activation or HIF-1α stabilization in tumor cells markedly upregulates the expression of oncogenic substrates such as HIF-1α and METTL14." (PMID 41583428, 2025). "The interplay between PRMT3 and c-MYC exemplifies the complex regulatory networks in tumor microenvironments, where PRMT3 orchestrates pro-tumorigenic signaling." (PMID 41583428, 2025). "BIN1, first identified as a pro-apoptotic tumor suppressor that interacts with and inhibits the oncogenic transcription factor MYC, has complex physiological roles." (PMID 40016843, 2025). "This approach has demonstrated preclinical efficacy in multiple myeloma models, inducing apoptosis in tumor cells through the deregulation of MYC-regulated circuits and the activation of pro-apoptotic genes such as BIM." (PMID 40940795, 2025). "PTTG1 modulates c-MYC expression and interacts with NF-κB signaling to support tumor cell proliferation and protect against apoptosis." (PMID 40072059, 2025). "The oncogenic properties of c-MYC lead to enhanced tumor proliferation and invasiveness, thereby contributing to the aggressive nature of PDEECs." (PMID 40072110, 2025). "Recent years have seen the identification of novel tumor immune escape mechanisms, some of which have been demonstrated to be directly or indirectly regulated by MYC." (PMID 40732268, 2025). "Herein, in this study, we explore some novel potential mechanisms through which MYC facilitates the immune evasion of tumor cells, alongside a combined therapeutic approach targeting MYC and employing immunotherapy based on this mechanism." (PMID 40732268, 2025). "The combination therapy promotes the PP2A-mediated suppression of oncogenic signaling through the concurrent inhibition of p-Akt and MYC, ultimately leading to tumor regression in preclinical models." (PMID 41146310, 2025). "Altogether, these results show that miR-218 mediates the effects of Notch signaling on suppressing MYC in TECs and normalizing tumor vessels." (PMID 40303332, 2025). "In the case of chr8q, gains are most frequently described as having tumor-promoting functions due to resulting MYC amplification." (PMID 41100815, 2025).
tumor (continued). "Reducing AZIN1 levels diminished MYC expression and suppressed cell cycle progression, ultimately inhibiting tumor growth." (PMID 40246846, 2025). "Simultaneously, treatment with PP2 significantly reduced nuclear PKM2 levels, suppressing the transcription of its downstream target genes (such as GLUT1, LDHA, and MYC) and markedly weakening tumor cells’ glycolytic capacity and proliferative ability." (PMID 41216192, 2025). "It has previously been reported that MYC-driven HCC requires HSF1 for tumor formation, and results from the current study support that this dependency also occurs in HGSOC." (PMID 39831777, 2025). "Actually, studies have highlighted that MYC not only plays a significant role in tumor development but also exhibits a dual role in the induction of DNA damage." (PMID 40290723, 2025). "The KRASG12V/MYC expressing tumor cells showed further characteristic features of cancer cells, such as a decreased cell size and cytoskeletal remodeling, increased migration and transwell invasion." (PMID 40550880, 2025). "The MYC oncogene family includes c-MYC, N-MYC, and L-MYC, among which c-MYC is the most extensively studied and is ubiquitously expressed during tissue development and in various tumor types." (PMID 41241099, 2025). "Meanwhile, co‐culture assay showed c‐MYC knockdown EG7 cells exhibited enhanced IFNγ secretion level of OT‐I cells as compared with that of control tumor cells, and I3A treatment further increased T cell activation levels." (PMID 40583248, 2025). "MYC plays a central role in carcinogenesis and is a key regulator of tumor development and drug resistance." (PMID 40290126, 2025). "Blockade of AZIN1 resulted in a significant delay of tumor progression and prolonged survival, even when using a MYC amplified MB tumor line." (PMID 39962590, 2025). "Remarkably, the clonal structure of MYC-amplified tumours was more complex (n = 3 of 7 cases), with the formation of three or more unique subclones (bottom)." (PMID 40335697, 2025). "MYC, TBX21 and BTN3A1 were found to be associated with the immune infiltration in the tumor tissues, especially related to the infiltration of T cells.As is well-known, a high infiltration of immune cells into tumors indicates better patient survival rates." (PMID 41343099, 2025). "The paediatric case carried an IGL::MYC translocation and was TdT‐positive in 40% of the tumour cells but CD34‐negative." (PMID 41047873, 2025). "The results showed that knockdown of MYC or TET3 alone significantly attenuated TMEM65‐induced xenograft tumor growth, and the more pronounced inhibitory effects were observed following simultaneous knockdown of MYC and TET3." (PMID 40546127, 2025). "Collectively, these mechanisms suggest that in HALs, virus-induced survival signals and oncogenic drivers, including MYC, converge to sustain tumor proliferation despite reduced BCL2 expression." (PMID 40496610, 2025). "We also demonstrate that I3A enhanced tumor immunogenicity by inducing c‐MYC degradation besides AhR degradation." (PMID 40583248, 2025). "NF2, TSC1, and PTPN12 were positively selected, indicating a potential tumour suppressing function for these genes, while MYC, HRAS, and PTPN11 were negatively selected, highlighting their oncogenic role." (PMID 40650785, 2025). "The amplification of MYC in relapsed or recurrent SCLC is driven by its critical role in tumor plasticity, heterogeneity, and resistance." (PMID 41023204, 2025). "This stabilization enhances the transcriptional activity of KLF4, which in turn activates the MYC oncogenic program, creating a feedforward loop that drives tumor progression." (PMID 40612941, 2025). "In parallel, tumor organoids were generated by randomly introducing GFP-tagged c-MYC overexpression via nucleofection using the Sleeping Beauty transposon system." (PMID 40917877, 2025).
tumor (continued). "Acyl-CoA synthase long-chain family member 4 (ACSL4) prefers arachidonic acid, and its overexpression stabilizes c-MYC through the ERK/FBW7/c-MYC axis, promoting tumor formation in vivo and in vitro." (PMID 41293169, 2025). "In summary, our study has elucidated the role of endothelial Notch-MYC pathway in TECs at the single cell level, and established TEC-targeted nanoparticles to normalize tumor vasculature by suppressing MYC." (PMID 40303332, 2025). "It has been demonstrated that inhibition of WNK1 by a specific inhibitor WNK463 effectively reduces the expression level of the senescence marker β-galactosidase and affects an oncogene MYC transcription, in tumor cells." (PMID 40510161, 2025). "We chose these metabolites specifically because we and others in the field have previously shown that glucose and glutamine catabolism is increased in MYC-driven tumours 7,21." (PMID 39880930, 2025). "Abnormal stimulation of the JAK2/STAT3/MYC pathway promotes tumor growth, metastasis, and drug resistance." (PMID 40944417, 2025). "We integrated these datasets with control-NESC H3K27me3 enrichment and analyzed differential peak calling with Diffbind39 to identify MYC-H3K27me3 bound promoters identified in human tumor lines (Table SX)." (PMID 41415380, 2025). "Given its central role and interactions with several key pathways in SyS, the overexpression of MYC in this tumor type highlights it as a potential target worth exploring for the development of new therapies aimed at slowing SyS progression." (PMID 40076599, 2025). "Since drawing CSF from patients is considered to be an invasive procedure, as a proof of concept, we quantified AZIN1 in the pre-and post-tumor resection surgery urine samples of two MB patients (with MYC amplification status)." (PMID 39962590, 2025). "MYC coordinates the metabolic processes in cancer cells to accommodate the dynamic tumor microenvironment." (PMID 40290126, 2025). "This heterogeneity of c-MYC expression within the cell population and between batches mirrors the variability observed in human tumors, highlighting the challenges of tumor modeling." (PMID 40917877, 2025). "The CTC-derived cell lines are able to independently form 3D structures that resemble the tumor of origin, retain positivity to EpCAM, and genetically exhibit 8q24.21 amplification containing the MYC oncogene." (PMID 40157906, 2025). "JQ1, a BET inhibitor, suppresses MYC-driven transcription, attenuates MM growth, and modulates the tumor microenvironment." (PMID 41403951, 2025). "Specifically, SP1 is known to regulate genes involved in cell cycle progression and DNA repair, while MYC promotes tumor survival through metabolic reprogramming." (PMID 40817807, 2025). "Both integrin‐FAK axis and MYC oncogene have been implicated in the regulation of pro‐metastatic traits of CRC such as cell motility, EMT, and tumor microenvironments." (PMID 40959971, 2025). "MYC not only drives proliferation and survival pathways but also fosters an immunosuppressive tumor microenvironment through modulation of immune-related gene expression." (PMID 40365020, 2025). "Inhibition of PLK1 reduces the phosphorylation of FBW7, preventing its autoubiquitination and proteasome degradation, thereby promoting the degradation of MYC and reducing tumor cell proliferation while increasing apoptosis." (PMID 40612941, 2025). "In tumor tissue, mutations in genes like KRAS, BRAF, and MYC impact polyamine metabolism, leading to an increase in polyamine content within the tissue." (PMID 40390766, 2025).